ENSG00000258864 (novel protein)
Gene: Protein-coding gene on chromosome 5 (112,827,213 to 112,867,582, forward strand). Ensembl gene ENSG00000258864.
Genetic constraint (gnomAD): Missense variants: 69 observed, 93.83 expected, observed/expected ratio (o/e) 0.74, 90% interval 0.61 to 0.9. Synonymous variants: 32 observed, 35.23 expected, observed/expected ratio (o/e) 0.91, 90% interval 0.69 to 1.22.